AURKC (aurora kinase C)
Diseases named in the same sentence as AURKC in open-access papers (continued):
Sharing a sentence is not in itself a finding about the gene and the disease.
cancer (27 papers, 2004 to 2025). A tumor composed of atypical neoplastic, often pleomorphic cells that invade other tissues. "The Aurora kinase family, which includes AURKA, AURKB, and AURKC, has been implicated in various cancers, with overexpression linked to chromosomal amplification of the AURKA gene." (PMID 40564876, 2025). "Altered function of MPS1 and AURKC have been shown to induce multipolar spindle phenotypes in murine oocytes and cancer cells, however, their role in reproductive aging associated oocyte aneuploidy is not known." (PMID 34026756, 2021). "Overexpression of AURKC in mitotic cells leads to centrosome amplification and multinucleation, a hallmark of cancer." (PMID 26347867, 2015). "Recent studies linked AURKC activity to tumorigenesis in somatic tissue, indicating that it may be a relevant cancer target." (PMID 29050234, 2017). "AURKC interactions with other proteins linked to cancer may also explain its oncogenic role." (PMID 26347867, 2015). "Although, the regulation and clinical implications of overexpressed AURKC in cancer cells are unclear, elevated levels of this enzyme were suspected to increase the proliferation, transformation, and migration of cancer cells." (PMID 34066975, 2021). "Kinase-dead AURKC inhibited HeLa cell proliferation, whereas constitutively active AURKC promoted cancer cell progression." (PMID 33257688, 2020). "In normal cells, the function of AURKC is predominantly restricted to meiosis; however, it is aberrantly expressed in various cancer cell lines, and contributes to oncogenesis." (PMID 29050234, 2017). "AURKC is overexpressed in many cancer cell lines, including NB1RGB, MDA-MB-453, HEPG2, HeLa, and HuH7, and in cancer of the reproductive tract." (PMID 26347867, 2015). "Aurora kinases A and B are found in various tissues, but the expression of Aurora kinase C is restricted in testis and its overexpression has been reported in certain cancer cells." (PMID 26141684, 2015). "Ongoing studies of normal AURKC functions in meiotic cells are critical to improving our understanding of the role of aberrant expression in cancer." (PMID 26347867, 2015). "Not until we have a complete understanding of the function and substrates of AURKC in meiotic cells can we begin to understand the significance of its expression in cancer cells." (PMID 26347867, 2015). "The biological significance of AURKC expression in cancer cells is also of clinical interest, but not well understood." (PMID 24586209, 2014). "Because these cells also express AURKB, studying the functions of AURKC in cancer cell division poses the same specficitiy difficulties as in oocytes." (PMID 24586209, 2014). "Taken together, our results demonstrate that the overexpression of active Aurora kinase C induces centrosome amplification and polyploidy, defects frequently observed in cancers cells." (PMID 22046298, 2011). "AURKC is known to be over expressed in several cancer cell lines while DAPK1 is a tumour suppressor candidate." (PMID 22087225, 2011). "Although studies have previously highlighted the potential therapeutic potential of AURKC, the mechanism by which AURKC promotes cancer remains unclear." (PMID 39895780, 2025). "Taken together, these results indicate that AURKC may serve as a prognostic biomarker for ccRCC, providing a theoretical basis for the development of new anti-cancer targeted drugs." (PMID 39895780, 2025). "In addition, research has shown that three members of the Aurora kinase family (AURKA, AURKB, and AURKC) play an important role in cancer cell migration and tumor progression." (PMID 36482411, 2022). "In cancer cells, the subcellular localization of AURKC is the same as that of AURKB suggesting that they could have similar functions." (PMID 34465813, 2021). "Relatively less information is available for the roles of AURKC in cancer." (PMID 33451333, 2021).
cancer (continued). "However, it is clear that the impact of HDAC inhibition on AURKA, AURKB, and AURKC expression is significant and should be used as an additive strategy for inducing cell cycle arrest and cell death in cancers where the AURK family of proteins are elevated." (PMID 34066975, 2021). "Hence, we postulate that AURKC-mediated serine phosphorylation of IκBα contributes to various types of cancer cell transformation." (PMID 29050234, 2017). "The functional significance of AURKC expression in cancer cells is unknown but may relate to centrosome regulation." (PMID 26347867, 2015). "Upregulation of CPC components, including AURKC, occurs in cancer cells and may correlate with clinical characteristics in primary colorectal cancers." (PMID 26347867, 2015). "AURKC is expressed in other cell types, including testes, neuronal tissue and some cancer cells." (PMID 24586209, 2014). "In recent years, aurora kinase C (AURKC) has emerged as a potential therapeutic target for cancer, having been found to induce proliferation in a variety of cancers." (PMID 39895780, 2025). "Many cancers aberrantly express AURKC, but because we do not fully understand AURKC function in its normal cellular context, it is difficult to predict the biological significance of this expression on the disease." (PMID 26347867, 2015). "AURKC is specifically expressed in testis where it plays a role in meiosis during spermatogenesis; its role in cancer development is not as clear as it is in the case of the other two family members, which are overexpressed in many different cancers, including hematological malignancies such as MM." (PMID 27655636, 2016).
tumor (22 papers, 2004 to 2025). "In the in vivo experiments, AURKC downregulation significantly inhibited the expression of ERp57 protein and blocked the growth of tumor tissue in tumor-bearing mice." (PMID 39895780, 2025). "To further verify that Danusertib exerts anti-tumor effects by inhibiting the AURKC/ERp57 pathway, we added Danusertib to SW839 cells and detected the expression of ERp57 by western blotting." (PMID 39895780, 2025). "Subsequently, cell models with knocked-down and overexpressed AURKC were constructed for in vitro cell experiments, and tumor-bearing mouse models were constructed to confirm the specific role of AURKC in vivo." (PMID 39895780, 2025). "These include three members of the Aurora kinase family (AURKA, AURKB, and AURKC), serin/thereonine kinases that regulate multiple aspects of tumor growth and progression." (PMID 36482411, 2022). "PLK1 and AURKC downregulation was also detected in BRDT-KO CaOV3 tumor tissues and in pOS-1 xenografts with BRDT shRNA injection." (PMID 33257688, 2020). "GSK 1070916, a potent inhibitor for AURKB and AURKC, has demonstrated anti-tumor growth capacity in a broad range of tumors." (PMID 33202573, 2020). "In the present study, we sought to confirm whether the small molecule inhibitor of AURKC can exert anti-tumor effects by inhibiting the AURKC/ERp57 pathway." (PMID 39895780, 2025). "In addition, cells overexpressing AURKC form colony foci on soft agar, and transplantation of these cells induces tumor formation in nude mice." (PMID 29050234, 2017). "AURKC induces abnormal cell division in cell lines, as well as tumor formation in nude mice." (PMID 29050234, 2017). "AURKC may promote tumor development in view of overlapping and complementary function with AURKB, as well as gene amplification and overexpression in cancers though the mechanism is still in dispute." (PMID 28147341, 2017). "Among the kinases that play a key role in promoting tumor proliferation, controlling mitosis progression, there are serine/threonine Aurora kinases, which include Aurora A (AURKA), Aurora B (AURKB) and Aurora C (AURKC)." (PMID 35884618, 2022). "AURKC was detected at different expression levels in tumour cell lines JURL-MK1, K562, MEG-01 and KG-1a, but was absent in the AML cell lines NB4 and NOMO-1." (PMID 33725274, 2021). "Downregulation of PLK1 and AURKC was detected in BRDT-knockout and BRDT-silenced tumor tissues." (PMID 33257688, 2020). "Al-Khafaji and colleagues demonstrated that, except AURKC, all other genes examined showed increased RNA gene expression in NSCLC tumor tissues compared to normal lung tissues, and only AURKA was significantly associated with a poor prognosis in NSCLC patients." (PMID 33202573, 2020).
infection (1 paper, 2024). The state of being infected such as from the introduction of a foreign agent such as serum, vaccine, antigenic substance or organism. "While these population-level effects are strong, data at the single-cell level indicate that subsets of EBV-infected cells in both early infection and LCLs retain or upregulate DZ mRNA for CXCR4, FOXO1, AICDA, IL2RB, AURKC, and LMO2." (PMID 38059622, 2024).
AURKC also shares sentences with these, for which no sentence is quoted: Globozoospermia (2 papers); infertile (2); thyroid cancer (2); bladder urothelial carcinoma (1); colon cancers (1); kidney cancer (1); medulloblastoma (1); renal carcinoma (1); stomach adenocarcinoma (1); Teratozoospermia (1); Wilms' tumour (1).